ALDOA (aldolase, fructose-bisphosphate A)
Diseases named in the same sentence as ALDOA in open-access papers (continued):
Sharing a sentence is not in itself a finding about the gene and the disease.
glioma (10 papers, 2015 to 2025). A benign or malignant brain and spinal cord tumor that arises from glial cells (astrocytes, oligodendrocytes, ependymal cells). "Survival analysis shows that hypomethylation of ALDOA in glioma and ovarian cancer is associated with significantly worse overall survival (p < 0.001 in glioma, p = 0.0388 in ovarian cancer)." (PMID 41239433, 2025). "We conducted several rescue experiments to validate the function of the circKIF4A-miR-335-5p-ALDOA axis in regulating glioma progression." (PMID 36030248, 2022). "The upregulation of circKIF4A facilitates glioma progression by means of binding miR-335-5p and upregulating ALDOA expression." (PMID 36030248, 2022). "The glycolysis regulating enzyme ALDOA was regulated by circKIF4A through the mechanism of interactivity with miR-335-5p in glioma cells." (PMID 36030248, 2022). "Overall, this study identified the biological function of the circKIF4A-miR-335-5p-ALDOA axis in glioma progression." (PMID 36030248, 2022). "Using qRT–PCR analysis, ALDOA was remarkably upregulated in glioma compared to adjacent-matched normal tissues." (PMID 36030248, 2022). "The glycolysis regulating enzyme ALDOA was regulated by circKIF4A through the mechanism of interacting with miR-335-5p in glioma cells." (PMID 36030248, 2022). "In a word, our data showed that the upregulation of circKIF4A facilitates glioma progression by means of binding miR-335-5p and upregulating ALDOA expression." (PMID 36030248, 2022). "ARST performed its function via regulating the dynamic equilibrium and integrity of actin cytoskeleton through ALDOA and cofilin, which in turn modified the morphology and invasive property of the glioma cells." (PMID 34099027, 2021). "Taken together, it is concluded that ARST performs its function via regulating the dynamic equilibrium and integrity of actin cytoskeleton through ALDOA and cofilin, which in turn modifies the morphology and invasive properties of the glioma cells." (PMID 34099027, 2021). "The NONHSAT138818.2, which we named lncRNA ARST (ALDOA related specific transcript) exhibited significant downregulation in the glioma tissues compared to the paracancerous and normal tissues." (PMID 34099027, 2021). "When we overexpressed ARST in the glioma cells, it interrupted the interaction of ALDOA and actin filaments, so that more binding sites of F-actin were exposed to cofilin, which in turn led to the depolymerization of actin cytoskeleton." (PMID 34099027, 2021). "The overexpression of ARST in glioma cells interrupted the interaction between ALDOA and F-actin cytoskeleton, which led to the rapid cofilin-dependent loss of F-actin stress fibers." (PMID 34099027, 2021). "Our results revealed that circKIF4A and ALDOA acted as endogenous competitive RNAs in glioma." (PMID 36030248, 2022). "Taken together, it is concluded that ARST performs its function via a non-metabolic pathway associated with ALDOA, which otherwise modifies the morphology and invasive properties of the glioma cells." (PMID 34099027, 2021). "However, the overall and disease-free survivals of the glioma patients with high level of ALDOA were obviously lower than that with low level of expression." (PMID 34099027, 2021). "Moreover, in vitro, ALDOA mRNA levels were down-regulated after glioma cell line SHC-44 cells treated with all-trans retinoic acid." (PMID 28191039, 2017). "Additionally, ALDOA was expressed at higher level in glioma cell lines." (PMID 36030248, 2022). "This research demonstrated for the first time that ARST acts as a tumor suppressor in GBM by a non-metabolic pathway associated with ALDOA, which may be a potential therapeutic target for glioma diagnoses, therapies, and prognoses." (PMID 34099027, 2021). "Furthermore, it was also reported that both ALDOA and cofilin could be used as promising indicators for glioma radio-sensibility and prognosis." (PMID 34099027, 2021).
glioma (continued). "According to our results, ALDOA was decreased after the suppression of circKIF4A in SHG-44 and A172 glioma cell lines." (PMID 36030248, 2022). "We selected seven glycolytic genes (HK2, PFKP, ALDOA, PGAM1, ENO1, ENO2 and PDK1) and confirmed their strong up-regulation under hypoxia by QPCR in seven GBM cell lines (five patient derived glioma stem-like cells and two adherent GBM cell lines)." (PMID 25932951, 2015). "Moreover, the assembly of RISC complexes of ALDOA mRNA was decreased after targeting circKIF4A in both SHG-44 and A172 glioma cell lines." (PMID 36030248, 2022). "Given that ARST suppressed gliomagenesis and ALDOA was a potential target of ARST, we next investigated whether ALDOA represented a functional link for the biological changes observed in the glioma cells with ARST upregulation." (PMID 34099027, 2021). "On the other hand, ALDOA protein expression revealed no statistical significance with the overall survival time in gliomas (p = 0.214)." (PMID 31450822, 2019). "However, in the glioma cells, downregulation of ARST decreases its restraint on ALDOA." (PMID 34099027, 2021).
colon carcinoma (9 papers, 2021 to 2025). "The association between ALDOA/AKT expression in colon cancer tissues and rectal cancer tissues in TCGA datasets was investigated via GEPIA platform." (PMID 38499636, 2024). "In contrast, POU2F1 or ALDOA deficiency had opposite effects and increased the frequency of apoptotic colon cancer cells." (PMID 34997215, 2022). "Following functional enrichment analyses for the differentially expressed genes were performed to investigate the potential biological processes in colon cancer influenced by the ALDOA gene." (PMID 39755705, 2025). "In colon cancer, ALDOA was shown to promote cell proliferation, clonogenicity, glycolysis, and PPP activity." (PMID 38744310, 2024). "For instance, study has showed that OCT1 binds the ALDOA promoter, enhancing activity and metabolic reprogramming to drive progression and drug resistance in colon cancer." (PMID 38605354, 2024). "As a hypoxia-inducible gene, ALDOA is a HIF1A target in its transcription and ALDOA gene expression is regulated by HIF1α in several tumors such as lung, liver and colon carcinoma cells with resistance and poor prognosis." (PMID 36077431, 2022). "Clearly, POU2F1 was paralleled with ALDOA expression in colon cancer cells and both of them acted as oncogenic factors to enhance the malignant behaviors of colon cancer." (PMID 34997215, 2022). "Together, these data indicated that POU2F1 enhanced the survival, proliferation, and clonogenicity of colon cancer cells by up-regulating ALDOA expression, enhancing the glycolysis and PPP activity, but attenuating the DNA damage-induced apoptosis." (PMID 34997215, 2022). "More importantly, POU2F1 or ALDOA also enhanced the oxaliplatin resistance in colon cancer cells in vitro." (PMID 34997215, 2022). "We found that ALDOA over-expression enhanced the proliferation and clonogenicity of colon cancer cells while ALDOA silencing had opposite effects (p < 0.05)." (PMID 34997215, 2022). "The impacts of POU2F1 on aldolase A (ALDOA) expression and malignant behaviors of colon cancer cells were examined." (PMID 34997215, 2022). "Our data indicated that POU2F1 directly bound to the ALDOA promoter and enhanced its activity in colon cancer cells." (PMID 34997215, 2022). "In our study, we found that POU2F1 or ALDOA over-expression not only reduced intracellular ROS, but also decreased γ-H2AX, a hallmark of DNA damage-related apoptosis in colon cancer cells." (PMID 34997215, 2022). "To further clarify the role of ALDOA in the progression of colon cancer, we constructed stably ALDOA over-expressing and silencing cells, respectively." (PMID 34997215, 2022). "We found that ALDOA expression was up-regulated in colon cancer tissues, consistent with previous observations." (PMID 34997215, 2022). "POU2F1 enhanced the proliferation, aerobic glycolysis and the pentose phosphate pathway (PPP) activity, but reduced oxidative stress and apoptosis in colon cancer cells, dependent on up-regulating ALDOA expression." (PMID 34997215, 2022). "To explore the role of ALDOA in colon cancer, we analyzed the expression and clinical significance of ALDOA in colon cancer." (PMID 34997215, 2022). "In this study, we employed the gain and loss of function strategies to determine the roles of POU2F1 and/or ALDOA in the glucose metabolism, proliferation and drug resistance of colon cancer in vitro and in vivo." (PMID 34997215, 2022). "Mechanistically, POU2F1 directly bound to the ALDOA promoter to enhance the ALDOA promoter activity in colon cancer cells." (PMID 34997215, 2022). "Thus, POU2F1 supported the oxaliplatin resistance in colon cancer cells, dependent on up-regulating ALDOA expression." (PMID 34997215, 2022). "However, it is still unclear how ALDOA expression is regulated and how ALDOA regulates glycolysis in colon cancer." (PMID 34997215, 2022). "Similarly, higher ALDOA expression was significantly associated with shorter OS and PFS of 184 colon cancer patients (p < 0.0001 for both)." (PMID 34997215, 2022).
colon carcinoma (continued). "Next, we tested the hypothesis that POU2F1 could directly induce ALDOA expression in colon cancer cells." (PMID 34997215, 2022). "Moreover, the levels of POU2F1 expression were correlated with ALDOA expression in 184 colon cancer tissues (R = 0.655, p < 0.001) and in colon cancer cell lines." (PMID 34997215, 2022). "Furthermore, POU2F1 enhanced the survival, proliferation, and clonogenicity of colon cancer cells by up-regulating ALDOA expression to enhance the glycolysis and PPP activity, and attenuating the DNA damage-induced apoptosis." (PMID 34997215, 2022). "Overexpression of ALDOA in colon cancer cells leads to the EMT progress." (PMID 35222014, 2021). "Therefore, both POU2F1 and ALDOA expression levels may be valuable biomarkers for the prognosis of colon cancer." (PMID 34997215, 2022). "Hence, targeting POU2F1 and/or ALDOA may be a promising strategy to overcome oxaliplatin resistance in colon cancer." (PMID 34997215, 2022). "We evaluated the gene expression correlation between AKT and ALDOA in the TCGA dataset using the GEPIA platform, and the results showed a positive correlation between the expression of AKT and ALDOA in colon cancer and rectal cancer tissues." (PMID 38499636, 2024). "We further tested the function of ALDOA in the POU2F1-enhanced glycolysis and PPP activity in colon cancer cells." (PMID 34997215, 2022). "Hence, ALDOA may act as an oncogenic factor of colon cancer." (PMID 34997215, 2022). "Together, these findings indicated that ALDOA enhanced the proliferation, glycolysis and PPP activity in colon cancer cells." (PMID 34997215, 2022). "Together, these data indicate that POU2F1 promotes the malignant behaviors of colon cancer by up-regulating the ALDOA expression, and the POU2F1 and ALDOA forms the axis to enhance the progression of colon cancer." (PMID 34997215, 2022). "In an acidic tumor microenvironment, fructose-bisphosphate aldolase A (ALDOA), pyruvate kinase muscle isozyme M2 (PKM2,) and lactate dehydrogenase A (LDHA) are overexpressed in colon cancer, resulting in high acidity of the intracellular environment." (PMID 33401375, 2021). "The paralleled expression of POU2F1 and ALDOA suggests that POU2F1 may induce ALDOA expression to regulate the glycolysis and PPP activity in colon cancer." (PMID 34997215, 2022). "It is notable that an alternation in the expression of POU2F1 or ALDOA did not significantly change the sensitivity to 5-FU in colon cancer cells." (PMID 34997215, 2022). "We found that POU2F1 transcripts were positively correlated with hexokinase 2 (HK2), 6-phosphofructo-2-kinase/fructose-2,6-biphosphatase 2 (PFKFB2), ALDOA, pyruvate kinase M1/2 (PKM), lactate dehydrogenase A (LDHA), G6PD, and ribose 5-phosphate isomerase A (RPIA) levels in the colon cancer tissues." (PMID 34997215, 2022). "Functionally, ALDOA also promoted the proliferation, clonogenicity, glycolysis and PPP activity, suggesting that ALDOA may act as an oncogenic factor to enhance the malignant behaviors of colon cancer." (PMID 34997215, 2022). "To further analyze the role of the POU2F1-ALDOA axis in oxaliplatin resistance of colon cancer cells in vivo, we established xenograft colon tumors by subcutaneously implanting with HCT116/L cells, HCT116/L-sh-POU2F1 cells, and HCT116/L-sh-POU2F1 + ALDOA cells into BALB/c nude mice." (PMID 34997215, 2022). "Interestingly, we found that POU2F1 and ALDOA expression were paralleled in colon cancer tissues and cell lines; altered POU2F1 expression modulated ALDOA expression in colon cancer cells; both POU2F1 and ALDOA expression appeared to a better biomarker for prognosis of colon cancer." (PMID 34997215, 2022). "Interestingly, further GSEA analysis revealed that the positive and negative signatures of YAP signaling cascade in colon cancer cells were significantly enriched (P were 0.002 and 0.006, respectively), which suggested the potential link between the ALDOA gene and this pathway." (PMID 39755705, 2025).
non-small cell lung carcinoma (9 papers, 2020 to 2025). A group of at least three distinct histological types of lung cancer, including non-small cell squamous cell carcinoma, adenocarcinoma, and large cell carcinoma. "In addition, ALDOA knockdown also conferred a tumor-suppressive effect on cervical adenocarcinoma and non-small cell lung cancer cells." (PMID 37403106, 2023). "Since both radiation and alkylating agents are important as adjuvant therapy for preventing recurrence and metastases in locally advanced non-small cell lung cancer, our results may provide new insights into improving clinical outcomes by targeting the novel ALDOA/PLD1 axis." (PMID 35127525, 2021). "Specifically, this study demonstrated that excessive ALDOA expression facilitated HCC proliferation and G1/S transition, whereas ALDOA knockout effectively curbed HCC proliferation both in vitro and in vivo, aligning with similar observations in non-small cell lung cancer." (PMID 40708574, 2025). "Importantly, we showed the short hairpin RNA (shRNA)-mediated attenuation of Set7/9 augmented c-Myc, GLUT1, HK2, ALDOA, and LDHA expression in non-small cell lung cancer (NSCLC) cell lines, not only at the transcriptional but also at the protein level." (PMID 34692483, 2021). "Two additional hallmarks of cancer metabolic reprogramming, ALDOA, and PGK1, were upregulated in keratinized OSCC, as indicated by increased glycolysis and metabolic reprogramming, which creates oncogenic stress, as suggested in other solid tumors, such as non-small cell lung cancer (NSCLC)." (PMID 32922662, 2020).
melanoma (7 papers, 2014 to 2025). A malignant, usually aggressive tumor composed of atypical, neoplastic melanocytes. "Compared with melanocytes, the mRNAs of ALDOA were highly expressed in human melanoma cell lines G361." (PMID 28191039, 2017). "It is worth to note that OP-A has been described as a calmodulin inhibitor and that calmodulin antagonists induce a reduction of ALDOA levels, coupled to cell death in melanoma cell lines." (PMID 27936075, 2016). "In the present study, the association between angiopoietin-like 4 (ANGPTL4) and aldolase A (ALDOA) in human melanoma cell invasion and survival was investigated." (PMID 24959248, 2014). "The results not only suggest an important functional role of ALDOA in ANGPTL4-enhanced melanoma cell survival, but also implicate ANGPTL4 and ALDOA in the development of melanoma chemoresistance." (PMID 24959248, 2014). "The results suggest that ALDOA is a critical mediator of the promoting effect of ANGPTL4 on melanoma cell invasion, likely through upregulating the MMP-2 expression." (PMID 24959248, 2014). "Since our findings had suggested that ALDOA was a downstream effector of ANGPTL4/PKC signaling, we investigated the functional roles of ANGPTL4 and ALDOA in melanoma cell invasion." (PMID 24959248, 2014). "Luciferase assays confirmed that ANGPTL4 could enhance ALDOA gene promoter/transcriptional activities in melanoma cells through a PKC-dependent mechanism." (PMID 24959248, 2014). "To examine the functional roles of ANGPTL4 and ALDOA in melanoma cell invasion, we performed in vitro cell invasion assays, which showed that ANGPTL4 overexpression increased cell invasion in WM-115 cells by over two-fold, which was reversed by knocking down ALDOA." (PMID 24959248, 2014). "To determine whether ANGPTL4 regulates ALDOA expression in human melanoma cells by altering the ALDOA gene promoter activity, we transfected WM-115 and WM-266-4 cells with human ALDOA promoter-luciferase reporter plasmids." (PMID 24959248, 2014). "The results suggest that ANGPTL4 expression may affect ALDOA expression in human melanoma cells at the gene transcription level through a PKC-dependent mechanism." (PMID 24959248, 2014). "Additionally, our results suggest that ALDOA plays an important role in ANGPTL4-enhanced melanoma cell survival against apoptotic stress, which implicates ANGPTL4 and ALDOA in the development of melanoma chemoresistance." (PMID 24959248, 2014). "It remains unclear whether ANGPTL4 and ALDOA may impact melanoma cell survival against other types of chemotherapy agents." (PMID 24959248, 2014). "To investigate the functional roles of ANGPTL4 and ALDOA in melanoma cell survival against apoptotic stress, we examined cell apoptosis in melanoma cells treated with 10 nM of cisplatin, an apoptosis-inducing chemotherapeutic agent commonly used to treat melanoma." (PMID 24959248, 2014). "Additionally, our results also suggest that ALDOA plays an important role in ANGPTL4-enhanced melanoma cell survival against cisplatin-induced apoptotic stress, which implicates ANGPTL4 and ALDOA in the development of melanoma chemoresistance." (PMID 24959248, 2014). "In the present study, ALDOA expression at both the mRNA and the protein levels was significantly increased and decreased in parallel with overexpression and knockdown of ANGPTL4 in melanoma cells, which was blocked by selective PKC inhibitor and restored by PKC agonist, respectively." (PMID 24959248, 2014).
bladder cancer (6 papers, 2020 to 2025). "A study also indicated that ALDOA was upregulated in bladder cancer and promoted bladder cancer malignant progression, while there is no report associated with TPI1 in bladder cancer." (PMID 38921479, 2024). "In cervical adenocarcinoma and bladder cancer, ALDOA affects tumor progression by regulating EMT process." (PMID 35804089, 2022). "ALDOA alterations are most frequent in invasive breast carcinoma (nearly 40%), primarily driven by amplifications, with significant frequencies also observed in bladder cancer, uterine tumors, and ovarian epithelial tumors." (PMID 41239433, 2025).
cardiac hypertrophy (5 papers, 2023 to 2025). "Glycolytic muscle aldolase (ALDOA), which binds to F-actin of the sarcomere and regulates cardiac hypertrophy, was regularly distributed across the Z-disc in AMD but appeared dislocated in ICM-DM (Fig. EV8E–J)." (PMID 40759793, 2025). "ALDOA, as a central enzyme in the glycolysis process, was identified as a metabolic regulator of cardiac hypertrophy by inhibiting AMPK activation." (PMID 39755705, 2025). "The ectopic expression of ALDOA plays an important role in the occurrence and development of myocardial hypertrophy, heart failure and many cardiovascular and cerebrovascular diseases." (PMID 38499636, 2024). "Therefore, blocking the AMPK inhibitory effect of ALDOA during cardiac hypertrophy would be beneficial in mitigating the progression of cardiac hypertrophy." (PMID 37938421, 2023). "However, overexpression of ALDOA has also been attributed to cardiac hypertrophy development." (PMID 40759793, 2025).